FBL (fibrillarin rRNA 2'-O-methyltransferase)
Description:
S-adenosyl-L-methionine-dependent methyltransferase that has the ability to methylate both RNAs and proteins. Involved in pre-rRNA processing by catalyzing the site-specific 2'-hydroxyl methylation of ribose moieties in pre-ribosomal RNA. Site specificity is provided by a guide RNA that base pairs with the substrate (By similarity). Methylation occurs at a characteristic distance from the sequence involved in base pairing with the guide RNA (By similarity). Probably catalyzes 2'-O-methylation of U6 snRNAs in box C/D RNP complexes. U6 snRNA 2'-O-methylation is required for mRNA splicing fidelity. Also acts as a protein methyltransferase by mediating methylation of 'Gln-105' of histone H2A (H2AQ104me), a modification that impairs binding of the FACT complex and is specifically present at 35S ribosomal DNA locus. Part of the small subunit (SSU) processome, first precursor of the small eukaryotic ribosomal subunit. During the assembly of the SSU processome in the nucleolus, many ribosome biogenesis factors, an RNA chaperone and ribosomal proteins associate with the nascent pre-rRNA and work in concert to generate RNA folding, modifications, rearrangements and cleavage as well as targeted degradation of pre-ribosomal RNA by the RNA exosome.
Synonyms: FLRN; RNU3IP1; FIB; Nop1
Tractability: Small molecule: a structure with a bound ligand is known. PROTAC: UniProt records ubiquitination sites on it; ubiquitination databases record sites on it; its protein half-life has been measured.
Target class: Enzyme; Transferase
Gene: Protein-coding gene on chromosome 19 (39,834,453 to 39,846,440, reverse strand). Ensembl gene ENSG00000105202.
Subcellular location: Nucleus, nucleolus; Nucleus, nucleoplasm
Subcellular location (Human Protein Atlas): Nucleoli fibrillar center; Nucleoplasm
Pathways (Reactome):
Metabolism of RNA: Major pathway of rRNA processing in the nucleolus and cytosol; rRNA modification in the nucleus and cytosol
Gene Ontology:
Molecular function: ATPase binding; histone H2AQ104 methyltransferase activity; protein binding; RNA binding; TFIID-class transcription factor complex binding; rRNA methyltransferase activity; methyltransferase activity; protein-glutamine N-methyltransferase activity; RNA 2'-O-methyltransferase activity; U6 snRNA 2'-O-ribose methyltransferase activity
Biological process: osteoblast differentiation; ribosomal small subunit biogenesis; rRNA methylation; snoRNA localization; box C/D sno(s)RNA 3'-end processing; maturation of SSU-rRNA; mRNA modification; rRNA 2'-O-methylation; rRNA processing; chromatin remodeling
Cellular component: box C/D methylation guide snoRNP complex; Cajal body; extracellular exosome; fibrillar center; membrane; nucleolus; nucleus; small-subunit processome; nucleoplasm; granular component; ribonucleoprotein complex
Genetic constraint (gnomAD): Loss-of-function variants: 9 observed, 38.39 expected, observed/expected ratio (o/e) 0.23, 90% interval 0.14 to 0.41. The upper end of that interval is the gene's LOEUF score, 0.41, which puts it in group 1 of 6, group 1 being the genes least tolerant of losing a copy. Missense variants: 340 observed, 432.06 expected, observed/expected ratio (o/e) 0.79, 90% interval 0.72 to 0.86. Synonymous variants: 163 observed, 166.87 expected, observed/expected ratio (o/e) 0.98, 90% interval 0.86 to 1.11.
Homologues: Orthologues: macaque FBL (99% identical), chimpanzee FBL (99% identical), guinea pig FBL (97% identical), dog FBL (97% identical), pig FBL (97% identical), mouse Fbl (96% identical), rat Fbl (96% identical), rabbit FBL (90% identical), tropical clawed frog fbl (82% identical), zebrafish fbl (81% identical), Drosophila melanogaster Fib (76% identical), Caenorhabditis elegans fib-1 (73% identical), and 1 more. Paralogues in human: FBLL1 (76% identical).
Diseases named in the same sentence as FBL in open-access papers:
FBL is named in the same sentence as 58 diseases in open-access papers, as found by Europe PMC text mining. Sharing a sentence is not in itself a finding about the gene and the disease. The quoted sentences say what the papers report.
breast carcinoma (18 papers, 2018 to 2026). "A significant association between FBL expression and prognosis was obtained from the analyses of 6 independent breast cancer series representing a total of 3,275 samples." (PMID 35545761, 2022). "Overall, these data support the existence of primary breast cancer tumors lacking detection of FBL protein associated with low mRNA levels of FBL that are associated with poor patient outcome at early stages of breast cancer." (PMID 35545761, 2022). "For instance, FBL contributes to tumorigenesis and is associated with poor survival in patients with breast cancer." (PMID 35464456, 2022). "Altogether, these data suggest that overexpression, but also and mainly underexpression, of FBL is associated with poor patient prognosis at an early stage of breast cancer." (PMID 35545761, 2022). "Clinically, the same authors have shown that FBL overexpression is associated with tumorigenesis and poor survival in patients with breast cancer and promotes cellular proliferation and resistance to doxorubicin chemotherapy of MCF7 breast cancer cells." (PMID 32241281, 2020). "Moreover, FBL overexpressing breast cancer cell lines exhibited increased cell proliferation and resistance to chemotherapy, reinforcing the association between FBL overexpression and poor survivals." (PMID 35545761, 2022). "For instance, in combination with tumor size, FBL expression led to the identification of patients with the poorest outcome although they harbored small tumors generally associated with a low risk factor in breast cancer patients." (PMID 35545761, 2022). "In addition, in breast cancer, high FBL expression levels are associated with a poor prognosis." (PMID 41233923, 2025). "As a result, the interaction between PTPN18 and FBL affects the proliferation and apoptosis of breast cancer cells, thus inhibiting tumor growth." (PMID 41559020, 2026). "FBL promotes cellular proliferation, colony formation, and resistance to doxorubicin in breast cancer cells." (PMID 40705480, 2025). "Our findings reveal that FBL expression is markedly higher in TNBC than in other breast cancer subtypes, providing direct evidence of its link to this aggressive tumor type." (PMID 41233923, 2025). "FBL contributes to mammary tumorigenesis and is overexpressed in several cancers, including breast cancer, acute myeloid leukaemia, prostate and liver cancers." (PMID 41233923, 2025). "Given its involvement in ribosomal pre-rRNA processing, FBL has emerged as a promising therapeutic target for certain cancers, including breast cancer." (PMID 39605984, 2024). "It has been proved that in breast cancer and prostate cancer, FBL can promote cancer cell proliferation by regulating mRNA translation and controlling rRNA methylation." (PMID 39605984, 2024). "In breast cancers, high expression of rRNA methyltransferase FBL accompanied by 2’-O-Me pattern modification is involved in impaired translational fidelity and downstream tumorigenesis." (PMID 37980347, 2023). "Altogether, we identified FBL as a powerful ribosome biogenesis-related independent marker of breast cancer outcome." (PMID 35545761, 2022).
breast carcinoma (continued). "Overall, these data indicate that the FBL mRNA level is an independent marker of poor patient outcome at an early stage of breast cancer." (PMID 35545761, 2022). "Altogether these data identify FBL as an independent marker of patient outcome at an early stage of breast cancer." (PMID 35545761, 2022). "FBL appears as a novel independent marker of poor patient outcome in breast cancer that belongs to the emerging field of ribosome in oncology." (PMID 35545761, 2022). "Fibrillarin (FBL), the mammalian homolog of Nop1 and snoRNAs are also overexpressed in breast cancer." (PMID 34299038, 2021). "In breast cancer, FBL expression alters rRNA 2′-O-methylation patterns, triggers changes in translational fidelity and promote cap-independent translation of IRES-containing mRNAs54." (PMID 29674660, 2018). "We previously demonstrated that elevated FBL mRNA levels are associated with poor survival in breast cancer patients, although this analysis did not focus on specific breast cancer subtypes." (PMID 41233923, 2025). "Importantly, the expression level of FBL itself was higher in the TNBC subtype compared to other breast cancer subtypes (ANOVA, p = 8.69 × 10–41)." (PMID 41233923, 2025). "Notably, FBL is generally a marker of poor prognosis in early-stage breast cancer, though a subset of aggressive tumors (∼10%) show reduced expression." (PMID 40918643, 2025). "Moreover, we showed that FBL overexpression in MCF7 breast cancer cell lines promotes cell proliferation, colony formation and resistance to doxorubicin." (PMID 35545761, 2022). "Interestingly, FBL remains an independent marker of poor prognosis at early stages of breast cancer even after adjustment against routinely used clinical gold standards." (PMID 35545761, 2022). "Therefore, FBL was identified as the only gene among the rRNA 2’-O-Me maturation complex of prognostic value in breast cancer." (PMID 35545761, 2022). "FBL might thus represent a strong biomarker of ribosome biogenesis in cancer, in particular in breast cancers." (PMID 35545761, 2022). "Here, we determine whether FBL is a marker of patient outcome at early stages of breast cancer that might reflect ribosome biogenesis activity." (PMID 35545761, 2022). "Conversely, O-GlcNAcylation could protect MCF-7 breast cancer cells against DOX by stabilizing box C/D small nucleolar ribonucleoprotein complexes (snoRNPs) core component fibrillarin (FBL) on Ser142 and maintaining ribosomal RNA methylation and ribosome assembly." (PMID 36059648, 2022). "To determine whether FBL is an independent marker of breast cancer outcome, we first performed univariate Cox regression analyses for NHP2L1, NOP56 and NOP58, the three factors associated with FBL in the rRNA 2’-O-Me maturation complex (C/D box snoRNP complex)." (PMID 35545761, 2022). "Indeed, FBL is overexpressed in prostatic neoplasia and breast cancer." (PMID 32241281, 2020). "Also, FBL overexpression is associated with poor survival in patients with breast cancer and promotes cellular proliferation and resistance to chemotherapy of MCF7 breast cancer cells." (PMID 30764532, 2019). "Internally, elevated FBL expression promotes the proliferation and resistance of MCF-7 breast cancer cells to chemotherapy." (PMID 39605984, 2024). "Concurrently, irradiated breast cancer cells display localization of GLI1 to the nucleolus as represented by clear colocalization of GLI1 and nucleolar markers UBF (UBTF) and Fibrillarin (FBL)." (PMID 37380890, 2023). "To determine whether the C/D box snoRNP complex signature differs in TNBC, we compared this signature (i.e., FBL, NOP56, NOP58, NHP2L1) in different breast cancer subtypes using the BRCA-TCGA dataset for the ribosome biogenesis signature." (PMID 41233923, 2025).
breast carcinoma (continued). "Second, when considering FBL, we observed that 16 out of the 44 tumour samples (36%) display no FBL staining at diagnosis, supporting our previous observation in breast cancer that some tumours express low level of FBL." (PMID 36370117, 2023). "Our data identify the rRNA methyltransferase FBL as a strong ribosome biogenesis-related prognosis biomarker in non-metastatic breast cancer patients." (PMID 35545761, 2022). "FBL expression at the protein level was analyzed by IHC in two TMAs: a test series of 389 primary breast tumors (CLB-1) and a validation series of 1,759 tumors (IGR-1) displaying characteristics of a classical breast cancer population." (PMID 35545761, 2022). "It has been reported that the knockdown of FBL is a negative factor for tumor growth in many cancers, such as breast cancer and prostate cancer." (PMID 36004921, 2022).
hepatocellular carcinoma (7 papers, 2019 to 2025). A malignant tumor that arises from hepatocytes. "High FBL expression is associated with larger tumor diameter, advanced tumor stage and a poor prognosis in hepatocellular carcinoma." (PMID 40705480, 2025). "In hepatocellular carcinoma (HCC), high FBL, MYC, and E2F levels are linked to lung metastases and poor prognosis." (PMID 41463151, 2025). "Silencing of FBL in hepatocellular carcinoma cells leads to reduced proliferation, migration, and invasion." (PMID 40705480, 2025). "In hepatocellular carcinoma, elevated FBL expression correlates with increased cell proliferation and enhanced metastatic potential." (PMID 40705480, 2025). "The expression of FBL is upregulated in several human cancers, including hepatocellular carcinoma and esophageal squamous cell carcinoma." (PMID 40705480, 2025). "The concentration of FBL mRNA in hepatocellular carcinoma tissues was significantly higher than that in normal liver tissues (p < 0.001)." (PMID 36004921, 2022). "The results showed that, compared with adjacent normal liver tissues, the expression of FBL in terms of the mRNA level and protein level in hepatocellular carcinoma tissues was upregulated, and the differences were statistically significant." (PMID 36004921, 2022). "Meanwhile, immunohistochemistry was used to detect FBL expression in 229 patients with hepatocellular carcinoma in our hospital." (PMID 36004921, 2022). "The expression of FBL mRNA was detected by RT-qPCR in 16 pairs of matched hepatocellular carcinoma tissues and adjacent normal liver tissues." (PMID 36004921, 2022). "As for hepatocellular carcinoma, further study is required to determine which gene plays the main regulatory role in FBL expression." (PMID 36004921, 2022). "In order to determine whether FBL is highly expressed in hepatocellular carcinoma, we analyzed FBL expression in samples of hepatocellular carcinoma tissue and normal liver tissue adjacent to the cancer in the TCGA and GSE14520." (PMID 36004921, 2022). "Knockdown of FBL could significantly reduce proliferation and stemness as well as inhibiting the migration and invasion of hepatocellular carcinoma cells." (PMID 36004921, 2022). "Furthermore, we found that FBL is highly expressed in hepatocellular carcinoma and that its high expression increases the rate of lung metastasis and indicates a poor prognosis." (PMID 36004921, 2022). "Our research preliminarily proves that FBL could affect the proliferation, stemness, migration, and invasion of hepatocellular carcinoma cells, which might be involved in the activation of MYC and E2F signaling." (PMID 36004921, 2022). "These three gene sets were BILE_ACID_METABOLISM, FATTY_ACID_METABOLISM, and ADIPOGENESIS, which suggests that FBL might be related to bile acid metabolism and fatty acid metabolism in hepatocellular carcinoma." (PMID 36004921, 2022). "In addition, in vitro or in vivo experiments were used to verify the effects of the FBL gene on the proliferation, stemness, migration, and invasion of hepatocellular carcinoma cells." (PMID 36004921, 2022). "Finally, we demonstrated that the knockdown of FBL could suppress hepatocellular carcinoma cell growth in vivo." (PMID 36004921, 2022). "However, the role of FBL in hepatocellular carcinoma cell growth in vivo is unclear." (PMID 36004921, 2022). "The hepatocellular carcinoma samples in the TCGA and GSE14520 databases were classified into FBL high expression or FBL low expression groups according to the median FBL expression." (PMID 36004921, 2022). "As a hub gene in ribosome-biogenesis-related proteins, FBL, which is closely related to the poor prognosis of HCC patients, can promote the growth and metastasis of hepatocellular carcinoma." (PMID 36004921, 2022). "Curiously, a few older studies revealed that patients with hepatocellular carcinoma (HCC), gastrointestinal, lung, and ovarian cancers have autoantibodies to FBL." (PMID 30764532, 2019).
hepatocellular carcinoma (continued). "The results of the survival analysis showed that high FBL expression was positively correlated with a shorter overall survival (OS) and shorter disease-free survival (DFS) in hepatocellular carcinoma patients, and the differences were found to be statistically significant." (PMID 36004921, 2022). "According to the immunohistochemistry results, we divided hepatocellular carcinoma patients into a low FBL expression group (Negative and Weak) and a high FBL expression group (Moderate and Strong), and the clinical data were sorted and analyzed according to the grouping." (PMID 36004921, 2022). "Moreover, we found that FBL might be involved in the regulation of MYC and E2F pathways in hepatocellular carcinoma." (PMID 36004921, 2022). "Moreover, in order to analyze the correlation between FBL expression and clinical prognosis in patients with hepatocellular carcinoma, we divided the two cohorts (TCGA and GSE14520) into a high-expressing FBL group and a low-expressing FBL group according to the median of FBL expression." (PMID 36004921, 2022).